AHR (aryl hydrocarbon receptor)
Diseases named in the same sentence as AHR in open-access papers (continued):
Sharing a sentence is not in itself a finding about the gene and the disease.
cancer (continued). "Further investigation of the regulatory role of AHR in the expression of MYCN may shed light, not only on the pathogenesis of NB, but also on a novel prevention or treatment for this devastating cancer." (PMID 24586395, 2014). "We did not observe ligand-dependent recruitment of the corepressor SMRT to the CXCR4 promoter and are currently investigating the role of other nuclear cofactors required for AHR-mediated suppression of CXCR4 and other genes in cancer cells treated with omeprazole." (PMID 25011475, 2014). "Interestingly, previous reports indicated TCDD stimulated EGFR activation in cancer cells, and TCDD-activated AhR can cross talk with EGFR signaling." (PMID 24927102, 2014). "Our findings and others clearly affirm the notion of AhR functioning in the progression of breast and other types of cancers, independent of its known ligands." (PMID 25068070, 2013). "Both cancer types frequently show an aberrant AhR expression, however, there is compelling evidence that the AhR can promote cancer formation independent of the presence of exogenous ligands." (PMID 20565777, 2010). "The AHR is a transcription factor known principally as a receptor for toxins such as 2,3,7,8-tetrachlorodibenzo-p-dioxin (TCDD), but it has other functions and appears to exert some anti-cancer effects." (PMID 21072210, 2010). "Whereas we found a statistically significant correlation between numerical centrosome aberrations and malignancy (dysplasia and cancer, p ≤ 0.0005, two-tailed Fisher exact probability test), no such correlation was detected for AhR overexpression alone." (PMID 20565777, 2010). "Notably, Acinetobacter radioresistens-derived IAA activates AhR/Wnt/β-catenin signaling to maintain intestinal stemness, whereas indole-3-lactic acid (ILA) inhibits STAT3 phosphorylation to suppress HK2-mediated glycolysis in cancer cells." (PMID 41488637, 2025). "In this study, we have analyzed the expression of AhR in a series of diffuse and intestinal gastric tumors, as well as the expression of xenobiotic metabolic enzymes such as cytochromes P450 (CYP1A1 and CYP1B1) and a large panel of genes known to be regulated by AhR in several cancers." (PMID 39200369, 2024). "One mechanism by which AhR supports chemoresistance is through the upregulation of the transporter ATP-binding cassette super-family G member 2 (ABCG2), which has been shown to export chemotherapy drugs in multiple cancers, including breast, choriocarcinoma, and nasopharyngeal and lung." (PMID 38339226, 2024). "AhR expression has not been analyzed across various cancer types using mIHC." (PMID 38680496, 2024). "While not yet approved for cancer therapy, the AhR agonist tapinarof is in clinical trials for atopic dermatitis and plaque psoriasis (NCT05142774, NCT05680740) and could potentially be tested for the treatment of dermatological malignancies in the future." (PMID 38807762, 2024). "However, this does not exclude other roles of PAHs and AhR in cancer development, which extends far beyond metabolic activation and genotoxic effects of PAHs." (PMID 37696458, 2023). "Overall, a small minority of detected cancer breakends (<1%) arose by AHR (including non-UPD LOH)." (PMID 37945902, 2023). "In this review, we will provide a general overview about the complex biology of AHR activation and not limit ourselves to cancer, because the effects of multiple mechanisms that modulate AHR activity have not yet been explored in the cancer context." (PMID 37696456, 2023). "This underscores that AHR activation does not necessarily promote cancer." (PMID 37696456, 2023). "AhR plays a central role in cancer promotion pointing towards the non-genotoxic properties of PAHs." (PMID 37696458, 2023). "Moreover, AhR, JAB1 (Jun-activation domain binding protein) and SMAD4 interacted and formed a complex that induced ubiquitination of SMAD4 in AhR-overexpressing H1299 cancer cells." (PMID 37830596, 2023).
cancer (continued). "PM2.5-exposure has also been shown to induce an AhR-dependent transcriptional activation of transmembrane serine protease 2 (TMPRSS2) and subsequent expression of the IL-1 family member IL-18 that may promote cancer progression." (PMID 37696458, 2023). "The fact that AhR intersects with multiple oncogenic signaling pathways suggests that the activation of AhR may offer therapeutic vulnerability in cancer cells where individual pathway components are not easily targeted or ‘druggable’ (e.g., c-MYC)." (PMID 37106727, 2023). "Therefore, identifying non-carcinogenic AhR agonist compounds is crucial for developing alternative cancer treatments." (PMID 35678668, 2022). "The purpose of the current investigation was to investigate the interaction between AhR and HIF-1 signaling pathways in A549 cells, which provide some experimental basis for scientists to find drugs that block AhR and HIF-1 signaling pathway to prevent and treat cancer." (PMID 35473600, 2022). "The goal of this study was to improve the understanding of the carcinogenic mechanism of BaP, clarify the interaction between AhR and HIF-1 signaling pathways, and provide an experimental basis for evaluating drugs to block the AhR and HIF-1 signaling pathways to prevent and treat cancer." (PMID 35473600, 2022). "The Candida albicans (C. albicans)-driven release of IL-7 from macrophages promotes aryl hydrocarbon receptor (AhR) and phospho-STAT3 (p-STAT3) binding at the IL-22 gene in ILC3s, which subsequently triggers the transcription of this cytokine for CAC formation in C. albicans AOM-DSS cancer model." (PMID 36341381, 2022). "As already mentioned, there is no recurrent AhR alteration in cancer." (PMID 33451095, 2021). "Furthermore, they discovered that Iso-3 alters the aryl hydrocarbon receptor (AHR) promoter methylation, increases the AHR expression in RAJI cells (25 μM; 72 h), and suppresses the growth of a large panel of cancer cell lines, with GI50 values between 7.3 and 14.8 μM." (PMID 34835969, 2021). "However, to our knowledge, interaction between AHR and sirtuin enzymes in cancer has not been established yet." (PMID 32117717, 2020). "Consequently, cancer cell induction of ‘exhaustion’ in NK cells and CD8+ T cells via kynurenine activation of the AhR may allow these cells to be a source of trophic support for CSC." (PMID 33375613, 2020). "The aryl hydrocarbon receptor (AhR) and aryl hydrocarbon receptor nuclear translocator (ARNT) complex is one of the transcription factors of NRF2, and the activity of this complex has been suggested to reduce cancer metastasis through increasing the expression of NRF232–34." (PMID 31527696, 2019). "Although a number of experiments have explored the relationship between AhR activity and various kidney diseases by analysing the target genes of AhR in both animal models and patients with CKD, AhR in kidney disease is still in its infancy compared with cancer and immune disease." (PMID 31488157, 2019). "Therefore, we cannot make firm conclusions about the lack of a role for the other MMPs in AHR-regulated invasion of cancer cell invasion." (PMID 29735912, 2018). "Another study using flow cytometry found that, in AhR-overexpressing cancer cells, 10% were in the S phase and none were in the G2/M phase and that increased expression of transcription factors, replication factors as well as proliferation of cell-nucleus antigens was observed." (PMID 29487603, 2018). "Raloxifene induces apoptosis in estrogen receptor-negative human cancer cells through the AhR." (PMID 29194351, 2017). "The contribution of the AHR to the later stages of cancer may be mediated by non-genotoxic endogenous ligands, which chronically drive AHR transcriptional activity." (PMID 26984638, 2016). "While these studies all point towards a role for the AHR in cancer stem-like cell generation, there is as yet no clear consensus on how this occurs or even on whether the AHR favors or inhibits BCSLC production/function." (PMID 26984638, 2016).
cancer (continued). "AhR-mediated non-genomic modulation of IDO1 might provide druggable targets in cancer therapy, in alternative to or in combination with the already available enzyme inhibitors." (PMID 25360135, 2014). "Several studies have identified a role for AhR in cancer independent of exogenous ligand." (PMID 24932473, 2014). "However, although factors impart available transcription factors to cancer cells, none of them specify the concrete targeting of AhR." (PMID 25226618, 2014). "Although TCDD, through AhR activation, may induce cancer, reproduction and neuronal dysfunctions, TEQ is unlikely to predict the risk of metabolic disorders induced by POP exposure." (PMID 22520265, 2012). "Therefore, it is possible that in some contexts AHRR mechanisms may be predominant as opposed to PARP7-DTX2-mediated degradation of AHR, and this may at least in part explain why certain cancer cell lines are resistant to PARP7 inhibition." (PMID 41326691, 2026). "However, the role of AhR in cancer is not as straightforward as we initially understood." (PMID 38518996, 2024). "Furthermore, we show that IL4I1, IDO1, or AHR high expression correlates with poorer survival of LGG patients, and that high IL4I1 expression also correlates with poorer outcome in GBM patients, confirming the clinical relevance of this pathway in these cancers." (PMID 38937431, 2024). "Finally, we discuss new and emerging strategies to therapeutically modulate AhR, focusing on novel agents that hold promise in current human clinical trials as well as existing FDA-approved drugs that could potentially be repurposed for cancer therapy." (PMID 38807762, 2024). "Furthermore, we show that IL4I1, IDO1, or AHR high expression correlate with poorer survival of LGG patients, and that high IL4I1 expression also correlates with poorer outcome in GBM patients, confirming the clinical relevance of this pathway in these cancers." (PMID 37986881, 2023). "While the impact of hypomethylation at cg18447419 on the action of AHR-mediated RhoA/Rac1 signaling is unknown, this CpG and SLC9A3 should be considered in future candidate analyses given the known interaction between this pathway and dioxin and its potential role in diseases like cancer." (PMID 33849548, 2021). "However, by comparing the transcriptional level with AhR activity score, in some cancers (BRCA, ESCA, HNSC, KICH, LIHC, PRAD and THCA) the transcription level partially matched the overall AhR activation, indicating that transcription level represented AhR activation in these cancers." (PMID 34290693, 2021). "In contrast to other studies involving AHR in cancer biology, this study was able to prove that AHR may act on the cell cycle even in the absence of an exogenous activating ligand, thereby suggesting a mechanism of action independent of its role as a xenobiotic receptor." (PMID 28649092, 2017). "Recently, several cancer cell lines have been reported to be sensitive to the antiproliferative effect of PARP7 inhibition by RBN2397; however, the roles of AHR and IFN-I signalling in this effect are not fully understood." (PMID 41432900, 2025). "AhR can activate EGFR through both traditional genomic signaling and nongenomic pathways, promoting cancer cell proliferation and resistance to EGFR–TKIs by activating proto-oncogene tyrosine-protein kinase Src (Src) signaling." (PMID 39578555, 2025). "The efficacy of 3-IAA and FOLFIRINOX is independent of AHR of immune and cancer cell origin, suggesting that 3-IAA-oxidized derivatives have anti-proliferative effects on cancer cells in a cell-intrinsic fashion." (PMID 37291097, 2023).
cancer (continued). "Hence, anti-inflammatory AHR activation may not be justified in cancer patients." (PMID 34559251, 2021). "The positive expression of AHR and CYP1A1 differed significantly (P < 0.01) between the normal and cancer groups." (PMID 34784845, 2021). "As would be expected, high AHR expression and activity was usually, although not always, correlated with up-regulated CYP1A1 and/or CYP1B1 in cancers of the GI tract, bladder, head and neck, and breast." (PMID 33396563, 2020). "The carcinogenic role of AhR/CYP1 family is supported by the fact that DMBA, a powerful breast-specific laboratory carcinogen, induces cancer in wild type, but not in cyp1 knockout, mice." (PMID 28103884, 2017). "When an expanded panel of human cancer cells was analysed, the correlation between the POU5F1 and AHR mRNA levels was still not obvious." (PMID 26059097, 2015). "Interestingly, immune checkpoint inhibitors (ICIs) whose use has been incorporated in the standard-of-care of multiple cancer types, were found to induce IL4I1 and activate AhR, thus generating a negative feedback loop." (PMID 38807762, 2024). "However, although many trials of AHR-targeted drugs and NRF2-target genes for cancer or disease have been conducted, most of them did not result in completed FDA approvals." (PMID 39404411, 2024). "AHR and HIF-1α are not oncogenes but are crucial regulators of transcription programs in the microenvironment as sensors/responders to microenvironment conditions in both cancer and immune cells." (PMID 34572746, 2021). "However, another agonist of AhR, TCDD, induces COX-2 (but not COX-1) transcription in cancer due to the presence of the AhR binding site (xenobiotic response elements, XRE) in the COX-2 promoter region." (PMID 27012456, 2016). "In general, these results suggest that non-toxic AHR modulators may represent important therapeutics for otherwise refractory TNBC and IBC, and potentially for brain and other cancers in which the AHR appears to play a role." (PMID 26984638, 2016). "The data identify novel roles for CREB and AhR as major, specific regulators of FSCN-1 transcription in human carcinoma cells but do not support the hypothesis that β-catenin signaling has a central role." (PMID 19340314, 2009). "However, in cancer types in which SLC7A5 is co-expressed with TDO and not with IDO (colon and rectum adenocarcinomas, lung adenocarcinoma and lung squamous cell carcinoma), AhR activation is likely to involve only TDO activity." (PMID 36286592, 2022).
infection (170 papers, 2007 to 2026). The state of being infected such as from the introduction of a foreign agent such as serum, vaccine, antigenic substance or organism. "As one example, conditional deletion of AhR in intestinal epithelial cells promoted increased susceptibility to infection." (PMID 40663393, 2025). "The top canonical pathways associated with the acute infection included “aryl hydrocarbon receptor signaling,” the “role of BRCA1 in DNA damage response” pathway, and the “activin-inhibin signaling” pathway (–log10[P] > 1.3, Benjamini-Hochberg–corrected)." (PMID 40662355, 2025). "AhR has been reported to be associated with the infection of many viruses, including Zika virus, human cytomegalovirus, SARS-CoV-2 virus, measles virus 40, and HIV." (PMID 40636257, 2025). "AHR signal transduction plays a potentially important role in maintaining immune homeostasis, reducing the risk of infection, and improving lung function in CF patients." (PMID 41155173, 2025). "Long-term deficiencies in CD8+ T-cell response in primary infection upon viral challenge are also observed following AHR stimulation, which is accompanied by changes in DNA methylation and gene expression." (PMID 38542367, 2024). "AhR takes part in the regulation of innate and adaptive immune responses to infection, whereas AhR deficiency exacerbates inflammation caused by some microorganisms." (PMID 39000041, 2024). "A recent study also reported that the AhR protects against P. aeruginosa infection, as AhR-deficient mice exhibited increased susceptibility to infection." (PMID 38790988, 2024). "The nuclear translocation of AhR is dependent on its binding to the intrinsic DNA domain, facilitating infection-associated accession in iNOS expression and neutrophil recruitment." (PMID 38680494, 2024). "Compared to wild-type C. elegans, nematodes unable to detect bacterial pigments via the aryl hydrocarbon receptor AhR were more susceptible to infection by Pf-free P. aeruginosa strains that over-produce pyocyanin." (PMID 36800381, 2023). "We next sought to understand what signals induced by infection cause such a decrease in lung endothelial AHR activity." (PMID 37587341, 2023). "In regard to immunity to infection, it was observed that susceptibility and mortality caused by Listeria monocytogenes or LPS were significantly increased in AhR-deficient mice compared to wild-type mice." (PMID 35203386, 2022). "We used Caco-2 cells co-cultured with C. albicans to verify the effect of AHR activation on cell damage caused by infection and the role of the MLCK-pMLC signaling pathway." (PMID 35923391, 2022). "Alternatively, AhR deficiency in vivo has been linked to chemical-induced tumorigenesis in infection models with DSS and Citrobacter rodentium." (PMID 34778104, 2021). "The effects of AhR in maintaining intestinal homeostasis were ablated in AhR-deficient mice and resulted in increased susceptibility of mice to Cr infection." (PMID 32230738, 2020). "The balance between the IDO1 and AhR pathways represents a surrogate for the status of the microbiota and the local immune system and a predictive factor for the susceptibility to infection and the disease course." (PMID 33322584, 2020). "AhR activation during IV infection disrupts host immunity and causes increased lung inflammation and mortality in mice." (PMID 32689931, 2020). "A higher number of naïve and activated CD4+ (CD4+CD44lowCD62Lhigh and CD4+ CD44highCD62Llow, respectively) T lymphocytes were observed in the lungs of AhR deficient mice at both post-infection periods studied." (PMID 32647342, 2020). "The lung histopathology of control and AhR−/− mice was evaluated after 10 weeks of infection and a higher number of yeast cells was observed in the lungs of the AhR-deficient mice." (PMID 32647342, 2020). "For instance, AHR-deficient mice infected with Listeria monocytogenes, an intracellular bacterium, were more susceptible to infection but developed enhanced resistance to re-infection." (PMID 31001262, 2019).